PDK3 (pyruvate dehydrogenase kinase 3)
Diseases named in the same sentence as PDK3 in open-access papers (continued):
Sharing a sentence is not in itself a finding about the gene and the disease.
tumor (29 papers, 2014 to 2026). "The goal was to find the most upregulated gene linked to tumor invasiveness, hence PDK3 was selected as a candidate for future testing." (PMID 34589439, 2021). "While PDK4 and PDK2 are expressed at lower levels, PDK1 and PDK3 are supposedly overexpressed in PCa and associated with advanced tumor stages." (PMID 33384955, 2020). "All three compounds also decreased the expression of HIF-1α and PDK3, indicating interference with hypoxia-driven metabolic adaptation, a process frequently exploited by tumor cells." (PMID 41614887, 2026). "By contrast, hepatic Pdk3 upregulation has been consistently observed across several models generated using different tumour-induction methods and in mice with varying genetic backgrounds, suggesting a more important role for Pdk3 in cachexia." (PMID 40275022, 2025). "In summary, we identified C14MC as a methylation‐driven tumor suppressor miRNA cluster and demonstrated that PDK3 is a direct target of C14MC." (PMID 38400534, 2024). "High PDK3 expression can drive glycolysis in tumor-resistant cells, increasing the hypoxic response of tumor cells and promoting glycolytic processes." (PMID 38671369, 2024). "PDK3, or pyruvate dehydrogenase kinase isoform 3, serves as a key regulator of intracellular energy metabolism, particularly within tumor cells." (PMID 39850812, 2024). "Researchers revealed that overexpression of PDK3 correlates with more advanced tumor stages, LNM, higher tumor grades, and increased mitotic index." (PMID 37801187, 2023). "Overexpression of PDK3 in tumor cells (HeLa, IMR32, and colo320DM cells) can increase metabolic conversion to glycolysis and increase the risk of drug resistance and tumor recurrence." (PMID 37818192, 2023). "PDK2 and PDK3 protein expression in tumor cells correlated with lower patient overall survival, whereas PDK1 protein expression correlated with higher patient survival." (PMID 37147361, 2023). "Our molecular gene profiling analysis suggests differences in the tumor microenvironment in groups of ccRCC tumors depending on PDK2/PDK3 expression." (PMID 37147361, 2023). "IHC and TCGA analysis showed that the expression of PKD3, the frequency and intensity of PDK3 nuclear staining, and the expression of Vimentin gradually increased with advanced tumour grade." (PMID 33692335, 2021). "High PDK3 expression significantly correlated with several pathologic variables such as high T stage, lymph node metastases, high tumor grade, vascular invasion, and high mitotic rate (all P < 0.001)." (PMID 34589439, 2021). "No significant statistical relationship existed between PDK1, PDK2, and PDK3 expression and tumor grade (P = 0.257, P = 0.395, P = 0.544)." (PMID 34220962, 2021). "In UBUC cohorts, T stage, lymph nodes metastases, high tumor grade, vascular invasion, peri-neural invasion, high mitotic rate, PDK1, and PDK3 overexpression were significantly associated with poor prognostic factors for DSS and MFS in univariate analysis." (PMID 34589439, 2021). "Altogether, these findings suggest that hepatic Pdk3 induction is a common response to tumours." (PMID 40275022, 2025). "Indeed, hepatic Pdk3 upregulation was observed in additional models generated using different tumour-induction methods and in mice with distinct genetic backgrounds." (PMID 40275022, 2025). "However, a comprehensive exploration of the distinct contribution of various PDK family members, particularly PDK3, across diverse tumor types remain incomplete." (PMID 38453992, 2024). "PDK3 (pyruvate dehydrogenase kinase 3) is another enzyme that promotes glycolysis in tumor cells." (PMID 37576511, 2023).
tumor (continued). "Moreover, DSS and MFS outcomes were significantly worse in cases where PDK3 in-tumor expression levels were higher (p < 0.0001 for both)." (PMID 37801187, 2023). "Importantly, we found a significant positive correlation of PDK2 and PDK3 immunostaining with lower overall survival (p = 0.021 and p = 0.022), and a positive correlation of PDK3 expression with higher tumor grade (p = 0.038)." (PMID 37147361, 2023). "Collectively, the results revealed that the mRNA level of PDK3 and its co-upregulated genes are strongly correlated with DNA replication and repair, suggesting that PDK3 might be important in tumor proliferation and development." (PMID 34589439, 2021). "PDK3 mRNA levels and its co-upregulated genes are strongly correlated with DNA replication and repair, suggesting that PDK3 may play a key role in tumor proliferation and development." (PMID 34589439, 2021). "Bioinformatic analysis revealed miR-3613-3p might regulate cell cycle signaling pathway by targeting SMS, PAFAH1B2, or PDK3 to restrain tumor progression." (PMID 33494814, 2021). "In univariate analysis at UTUC, tumor location, multi-focal tumors, T stage, lymph node metastases, vascular invasion, high tumor grade, peri-neural invasion, PDK1 overexpression, and PDK3 overexpression were all found to be significantly associated with poor prognostic factors for MFS and DSS." (PMID 34589439, 2021). "In addition, PDK3 (pyruvate dehydrogenase kinase 3) had been reported to regulate tumor cell differentiation and cell fate." (PMID 33043022, 2020). "Similarly to PDK1, PDK3 is induced by HIF-1α, and higher expression is associated with higher tumor stage in many cancers." (PMID 33384955, 2020). "Accordingly, the suppression on PDK3 by metformin may contribute to its anti-tumor activity in LoVo cells." (PMID 26616174, 2015). "Additionally, miR-3613-3p might regulate cell cycle by targeting SMS, PAFAH1B2, or PDK3 to restrain tumor progression." (PMID 33494814, 2021). "Analysis of PDK3 expression in our cohort of 10 normal and SCC samples revealed significant upregulation of PDK3 in tumor samples." (PMID 38400534, 2024). "Gene expression data of microdissected stroma from normal breast and TNBC31 showed significant downregulation of PDK2 and low levels of PDK1, PDK3 and PDK4 in the tumour stroma similarly to our CAFs." (PMID 35760868, 2022). "The hidden links between PDK1, PDK2, PDK3, and PDK4 expression and tumor-infiltrating immune cells in GC were assessed by the TIMER database." (PMID 34220962, 2021).
metabolic disease (2 papers, 2020 to 2025). A congenital disorder (due to inherited enzyme abnormality) or acquired (due to failure of a metabolically important organ) disorder resulting from an abnormal metabolic process. "Another finding with support in the literature is that of SNP rs10126793 - its upstream gene PDK3 or pyruvate dehydrogenase kinase 3 is in the class of PDK isoenzymes that have been shown to be strong therapeutic targets for preventing and treating metabolic diseases." (PMID 32894123, 2020).
PDK3 also shares sentences with these, for which no sentence is quoted: peripheral neuropathy (3 papers); infection (2); ovarian carcinoma (2); Ataxia (1); Charcot-Marie-Tooth disease, type 6 (1); developmental delay (1); head and neck squamous cell carcinoma (1); hereditary corneal dystrophies (1); liver disease (1); Neurodevelopmental delay (1); neurodevelopmental disorder (1); neuropathy (1); Obesity (1); optic atrophy (1); osteoarthritis (1); polymicrogyria (1); triple-negative breast carcinoma (1).